NOX1 (NADPH oxidase 1)
Diseases named in the same sentence as NOX1 in open-access papers (continued):
Sharing a sentence is not in itself a finding about the gene and the disease.
liver fibrosis (continued). "Angiotensin II (Ang II) also induces NOX1 to promote HSCs proliferation and aggravate liver fibrosis." (PMID 26222337, 2015). "NOX2, for instance, was shown to participate in neovascularization, neurotransmitter release and liver fibrosis while NOX1 was reported to play a pivotal role in the pressor response to Ang II and to be involved in inflammatory pain." (PMID 24466344, 2014). "Due to the generation of ROS, NOX1, 2 and 4 promote hepatic fibrosis by participating in multiple processes, including HSC activation, proliferation, survival, and migration, hepatocyte apoptosis, enhancement of fibrogenic mediators, and mediation of an inflammatory cascade in both KC and HSC." (PMID 37627562, 2023). "In addition, deficiency of either NOX1 or NOX4 reduced lipid peroxidation and ROS production in mice with liver fibrosis, leading to attenuated liver injury, inflammation, and fibrosis." (PMID 36830722, 2023). "Specifically, setanaxib has been described to replicate the beneficial effects seen in multiple NOX1/4 KO models of liver fibrosis, reducing oxidative stress, hepatocyte apoptosis, inflammation and fibrosis in different types of CLD, including NASH, bile duct ligation and CCl4 treatment." (PMID 37627562, 2023). "For example, during liver fibrosis, Aoyama and colleagues revealed that the excessive activation of NOX1 in hepatic stellate cells upregulated NOX4 expression, which greatly induced ROS generation and suggested that NOX1/4 were promising therapeutic targets for liver fibrosis." (PMID 35386842, 2022). "Further review of the literature showed that both TGFβ1 and AngII could upregulate the expression of NOX4, and GKT137831, a dual inhibitor of NOX1/4, could inhibit the production of ROS and hepatic fibrosis." (PMID 34135982, 2021). "Therefore, targeting NOX1/4 is emerging as a new and attractive therapy for liver fibrosis in order to impair the pathological effects of TGF-β over this disease." (PMID 30250825, 2018). "NOX isoforms, including NOX1, NOX2 and NOX4, and NOX-derived ROS, have all been implicated to regulate HSC activation and hepatocyte apoptosis, both of which are essential steps for initiating liver fibrosis." (PMID 26869935, 2016). "NOX1 or NOX4 deficiency reduced lipid peroxidation and ROS production in mice with liver fibrosis." (PMID 26222337, 2015). "Deficiency of NOX1 and NOX4 attenuates liver fibrosis in mice after CCl4 treatment." (PMID 26222337, 2015). "Here we report for the first time a direct comparison of the long-term effects of NOX1 and NOX4 deficiency in the development and progression of liver fibrosis, by comparing liver fibrosis in CCl4-induced NOX1KO and NOX4KO mice and their respective wild-type (WT) littermates." (PMID 26222337, 2015). "We report for the first time a direct comparison of the long-term effects of NOX1 and NOX4 deficiency in the development and progression of liver fibrosis, by comparing liver fibrosis in CCl4-induced NOX1KO and NOX4KO mice and their respective wild-type (WT) littermates." (PMID 26222337, 2015). "Thus, we hypothesize that deficiency of either NOX1 or NOX4 attenuates HSCs activation and liver fibrosis." (PMID 26222337, 2015). "NOX1 has been shown to be involved in the progression of NAFLD and the aggravation of liver fibrosis." (PMID 36830722, 2023). "NOX1 expression in HSCs becomes upregulated following both carbon tetrachloride (CCl4)‐ and bile duct ligation (BDL)‐induced liver fibrosis." (PMID 36658776, 2023). "The expression of NOX1 and NOX2 was increased in the mouse model of liver fibrosis with CCl4 and bile duct ligation (BDL)." (PMID 36544529, 2022). "NOX1, NOX2, and NOX4 are involved in initiating liver fibrosis, and NOX4 plays a role in mediating TGFβ-1 signaling which is crucial in IPF development." (PMID 35740948, 2022).
liver fibrosis (continued). "Experimental liver fibrosis induced by carbon tetrachloride was attenuated in both NOX1 and NOX4-knock-out mice and this effect was reproducible by treatment with a dual NOX1/NOX4 inhibitor." (PMID 35740032, 2022). "In this study, the effects of human exosomes derived from WJ-MSCs on NOX1, NOX2, and NOX4 gene expression in TGF-β-induced hepatic fibrosis were investigated." (PMID 36544529, 2022). "HSCs produce NOX1, NOX2, and NOX4, which play substantial roles in the process and development of liver fibrosis." (PMID 36544529, 2022). "NOX-es are also involved in activating HSCs, responsible for liver fibrosis, and this mechanism itself can trigger upregulation of diverse NOX isoforms (NOX1, NOX2 and NOX4), creating a vicious cycle and potentially sustaining the progression toward HCC." (PMID 35740032, 2022). "The ROS-generating enzymes, NADPH oxidase 1 (NOX1), NOX2, or NOX4, can induce liver fibrosis by activating HSCs." (PMID 34675811, 2021). "The treatment with atorvastatin ameliorated liver fibrosis in the BDL+At group by the down-regulation of Rac1-GTP, Rac1, and NOX1, as well as the elevation of antioxidant molecules (thiols, SOD, and catalase)." (PMID 32395205, 2020). "Inhibition of NOX1/NOX4 using GKT137831 attenuated CCl4 or BDL-induced ROS production and hepatic fibrosis in mice." (PMID 26869935, 2016). "A number of NOX isoforms, including NOX1, NOX2, and NOX4 are involved in the initiation of myofibroblasts activation and progression hepatic fibrosis." (PMID 26869935, 2016). "The overall goal of this study was to determine the roles of NOX1 and NOX4 on the proliferative and fibrogenic phenotypes of HSCs and its contribution to liver fibrosis." (PMID 26222337, 2015). "In conclusion, our current study demonstrates that NOX1 and NOX4 signaling mediates hepatic fibrosis through activation of HSCs." (PMID 26222337, 2015). "Our data demonstrated that NOX1 and NOX4 gene deletion inhibits multiple steps in the pathogenesis of liver fibrosis." (PMID 26222337, 2015). "Our results demonstrate that both NOX1 and NOX4 play important roles in liver fibrosis in HSCs, and that NOX4 has a more robust role in the activation of HSCs." (PMID 26222337, 2015). "Our results support the concept that both NOX1 and NOX4 play important roles in liver fibrosis in HSCs, and that NOX4 has a more robust role in the activation of HSCs." (PMID 26222337, 2015). "A role for the NADPH oxidases NOX1 and NOX2 in liver fibrosis has been proposed, but the implication of NOX4 is poorly understood yet." (PMID 23049784, 2012). "Actually, NOX1 and NOX4 signaling mediates hepatic fibrosis through activation of HSC." (PMID 30250825, 2018). "Moreover, the NOX1 inhibitor, GKT-136901, has been shown to be able to suppress liver fibrosis induced by bile duct ligation." (PMID 29977014, 2018). "Recent evidences show up the dual role of NOX1/NOX4 pharmacological inhibitors in decreasing both the apparition of fibrogenic markers and hepatocyte apoptosis in vivo, highlighting the relevance of NOX1 and NOX4 in liver fibrosis and opening new perspectives for its treatment." (PMID 30250825, 2018). "In addition to the TGFβ-NOX4 axis-mediated activation of HSC and expression of fibrogenic factors, other NOX isoforms, including NOX1, NOX2, and NOX2 regulatory subunit p47phox, are also reported to orchestrate the progression of hepatic fibrosis." (PMID 26869935, 2016). "Recently, small molecule NOX1/4 dual inhibitors such as GKT137831 have been developed that show good orally bioavailability and tolerability when administered orally in animal model of pulmonary fibrosis and liver fibrosis." (PMID 26222337, 2015). "Previous studies by us and others demonstrated that GKT137831 attenuated liver fibrosis and ROS production as well as fibrotic genes in both the CCl4 and BDL models of liver fibrosis, suggesting that NOX1/4 may be a new therapy for liver fibrosis." (PMID 26222337, 2015).
liver fibrosis (continued). "Among the NOX family, both NOX1 and NOX4 are expressed in HSCs and may contribute to liver fibrosis." (PMID 26222337, 2015). "Thus, NOX1 and NOX4 signaling mediates the pathogenesis of liver fibrosis, including the direct activation of HSC." (PMID 26222337, 2015). "The effect of NOX1 and NOX4 deficiency in liver fibrosis is unclear, and has never been directly compared." (PMID 26222337, 2015). "This review synthesizes current knowledge on the molecular pharmacology of the NOX1/4 axis, preclinical evidence from translational models, and clinical trial outcomes to critically assess the therapeutic potential of targeted NOX inhibition in hepatic fibrosis." (PMID 41516036, 2025). "Targeting specific NOX isoforms with specific inhibitors, such as NOX1 and/or NOX4 to prevent HSC activation and protect hepatocyte injury may be promising to treat liver fibrosis, although future work is needed to fully confirm the clinical safety of these compounds." (PMID 26869935, 2016). "Therefore, we aimed to determine the role of NOX1 and NOX4 in liver fibrosis, and investigated whether NOX1 and NOX4 signaling mediates liver fibrosis by regulating HSC activation." (PMID 26222337, 2015). "Activated HSC and ROS generation are also attenuated in HSC lacking NOX1 and NOX4, suggesting NOX1 and NOX4 play important roles in liver fibrosis and injury through regulating inflammation, proliferation and fibrogenesis in HSC." (PMID 30250825, 2018). "Activated HSCs and ROS generation are also attenuated in HSCs lacking NOX1 and NOX4, suggesting NOX1 and NOX4 play important roles in liver fibrosis and injury through regulating inflammation, proliferation and fibrogenesis in HSCs." (PMID 26222337, 2015).
colorectal cancer (23 papers, 2014 to 2025). A primary or metastatic malignant neoplasm that affects the colon or rectum. "NOX1 inhibition decreased tumor angiogenesis and lymphangiogenesis and modulated the composition of tumor-associated immune cells in colorectal cancer by promoting the recruitment of immune/inflammatory cells consistent with the observed decrease in tumor growth." (PMID 31249132, 2019). "As p38 MAPK inhibitor are now under clinical evaluation for colorectal cancer treatment, it is interesting to consider that a strategy leading to maximize Nox1 activity associated to the inhibition of p38 MAPK would be beneficial for patients, particularly those resistant for oxaliplatin treatment." (PMID 29262595, 2017). "Here we generated the IL10/Nox1dKO mouse model which combines immune dysfunction (IL-10 deficiency) and abnormal epithelium (NADPH oxidase 1 (Nox1) deficiency) and spontaneously develops a UC-like phenotype with similar complications (colorectal cancer) than UC." (PMID 25014110, 2014). "Mut1 increases ROS production through Nox1 activity affects mitochondrial organization and increases cytotoxicity in colorectal cancer cell lines." (PMID 36902094, 2023). "A NOX isoform NOX1 was reported to be expressed in human colonic epithelial cells and colorectal cancer cells and another NOX isoform NOX2 was expressed in innate immune cells, such as neutrophils and macrophages." (PMID 33503019, 2021). "It was also reported that Kras G12V (K-ras V12) promotes ROS production in colorectal cancer cells through activation of the p38-PDPK1-PKCδ/p47phox-NOX1 cascade, which promotes malignant transformation." (PMID 33217967, 2020). "We employed our NOX1 antibody to characterize NOX1 expression in a panel of 30 human colorectal cancer cell lines, and correlated protein expression with NOX1 mRNA expression and superoxide production in a subset of these cells." (PMID 32428030, 2020). "Previous studies reported that mutant KrasG12V (K-ras V12) promotes the reactive oxygen species (ROS) production in colorectal cancer cells through activation of the p38-PDPK1-PKCδ/p47phox-NOX1 cascade, which promotes malignant transformation." (PMID 33217967, 2020). "Here, we show that GKT771, a novel, potent, and highly selective pharmacological inhibitor of NOX1, or genetic deletion of NOX1 in mice reduced tumor growth in preclinical models of colorectal cancer and melanoma in immunocompetent mice." (PMID 31249132, 2019). "Based on these results, we propose blocking of NOX1 by GKT771 as a potential novel therapeutic strategy to treat colorectal cancer, particularly in combination with checkpoint inhibition." (PMID 31249132, 2019). "This is an unexpected result, as NOX1 gene silencing experiments demonstrated that NOX1 promotes colorectal carcinoma cell proliferation and cell cycle progression leading to increased tumor growth." (PMID 31249132, 2019). "After establishing oxaliplatin-resistant colorectal cancer lines, we observed that these cell lines showed an increase in Nox1 and calpain activity." (PMID 29262595, 2017). "To investigate the clinical relevance of our findings, we examined the relationship between expression levels of NOX1 and IL-4Rα in human colorectal cancer surgical specimens and adjacent uninvolved bowel mucosa by real time RT-PCR." (PMID 28498822, 2017). "NOX1 inhibition, alone or in combination with checkpoint inhibitors, may, therefore, represent a promising antitumor strategy in colorectal cancer." (PMID 31249132, 2019).
colorectal cancer (continued). "The level of expression of Nox1 and some of its regulatory partners is known to be increased in colorectal cancer and could explain the increase in Nox1 activity observed in our resistant cells." (PMID 29262595, 2017). "However, studies of NOX1 expression in Caco-2 human colorectal cancer cells demonstrated that binding of the transcription factor GATA6 to the NOX1 promoter played an important role in the regulation of NOX1 expression." (PMID 28498822, 2017). "We also investigated the potential clinical-pathological relevance of NOX1, ADAM17, and MCAM expression in colorectal cancer." (PMID 38137406, 2023). "It has been reported that NADPH-oxidase family members, in particular NOX1 and NOX4, are expressed by cancer cells and promote tumor growth and metastasis in several cancers (i.e., melanoma, gastric, pancreatic, and colorectal cancers)." (PMID 38137406, 2023). "Especially, the expression of MCAM, NOX1, and ADAM17 was more prominent in the angiogenic, colorectal cancer-consensus molecular subtype 4 where high MCAM expression correlated with angiogenic and lymphangiogenic markers." (PMID 38137406, 2023). "We found that both cytokines increased the expression of NOX1 (but not other NOX species) over a period of 12 to 48 h in a panel of human colorectal cancer cell lines that possess the Type II IL-4R." (PMID 28498822, 2017). "PCR conditions were validated by using the colorectal cancer cell line caco-2 and the prostate cancer cell line LNCaP as a positive control for Nox1 and 5, respectively (data not shown)." (PMID 24629065, 2014). "To test these hypotheses, we monitored NOX1, ADAM17, and mMCAM protein expression and performed co-immunoprecipitation (co-IP) experiments from whole lysates of human endothelial cells (HUVEC) and human colorectal cancer (CRC) cell lines (HCT-116, DLD1, and SW480)." (PMID 38137406, 2023).
colitis (21 papers, 2014 to 2025). Inflammation of the colon. "Our results are consistent with a previous report that indirectly implicated PTEN in mucosal repair after DSS-induced colitis in mice, following its inhibitory oxidation by formyl peptide receptor-induced NOX1 activation and reactive oxygen species production." (PMID 40723233, 2025). "In the case of NOX1 inactivating NOX1-3 (Cybanmf333) in mice was sufficient to cause severe colitis upon challenge, mainly due to mucus barrier and host defense failure." (PMID 37820403, 2023). "Salubrinal has been shown to relief colonic inflammation in mice with deficiency in IL-10 and NADPH oxidase 1 or DSS-induced colitis." (PMID 35685885, 2022). "Given the findings of our present study, we conclude that IL-4Rα deficiency enhances NOX1-dependent ROS production and intestinal mucosal barrier function, resulting in the suppression of colitis development." (PMID 33192516, 2020). "NOX1-deficient mice showed reduced susceptibility to trinitrobenzene sulfonic acid-induced colitis through downregulation of proinflammatory cytokine expression in macrophages." (PMID 33192516, 2020). "In line with this, human genetic studies have found that loss-of-function mutations in ROS-producing enzymes predispose to IBD: patients (especially with very-early-onset IBD) carrying defective NOX2 (as in chronic granulomatous disease) or mutations in NOX1/DUOX2 often develop colitis." (PMID 40860650, 2025). "However, pathogenic roles of NOX1-derived ROS in colitis have also been reported." (PMID 33192516, 2020). "ROS's protective role was directly demonstrated in a study, for example, that showed that mice with genetic ablation of NOX1 had impaired mucosal repair following DSS-induced colitis." (PMID 40860650, 2025). "In the DSS-induced colitis group, the expression levels of 8-OHdG, NOX1, and NOX2 in colon tissue were significantly higher than those in the normal control group." (PMID 32337275, 2020). "Our results indicate that the development of DSS-induced colitis is alleviated in IL-4Rα-/- mice through enhancement of NOX1-derived ROS production in the colon." (PMID 33192516, 2020). "To verify the transcriptome analysis results, we conducted qPCR to measure the mRNA expression level of Nox1 in colitis mice." (PMID 33192516, 2020). "To evaluate the antioxidant effects of IG in a DSS-induced colitis model, we analyzed the levels of 8-OHdG, NOX1, and NOX2." (PMID 32337275, 2020). "Seemingly in contrast to our findings, NOX1 expressed in macrophages has been shown to play a role in the pathogenesis of colitis in a mouse model and NOX2-derived ROS was demonstrated to be involved in the development of necrotizing enterocolitis." (PMID 29734661, 2018). "We have recently demonstrated that knock-out of NOX1 prevents the development of chronic colonic inflammation in a genetically engineered mouse model of the pre-malignant condition, inflammatory bowel disease." (PMID 28330872, 2017). "DUOX2 expression was also increased; however, this increase was moderate as compared to that of NOX1, suggesting a predominant role of NOX1 in TNFα-induced colitis." (PMID 25276054, 2014). "For example, in animal models, could enhancing epithelial NADPH oxidase activity (e.g., by administering low levels of ROS donors or gene therapy to boost NOX1/DUOX2 function) reduce colitis severity?" (PMID 40860650, 2025). "This hypothesis was further substantiated by the fact that the oxidative inactivation of PTEN and PTPN12 by NOX1 enhanced wound repair in the DSS experimental mouse model of colitis." (PMID 40723233, 2025). "NOX1 is reported to be highly expressed in colon tissue, but its role in colitis is still unclear." (PMID 37239114, 2023). "Indeed, through up-regulation of chemokines, inflammatory cytokines and iNOS, NOX1/NADPH oxidase has a vital role in the TNBS-induced colonic inflammation pathogenesis, according to past studies." (PMID 35774596, 2022).